CATSPERT (catsper channel auxiliary subunit tau)
Description:
Auxiliary component of the CatSper complex, a complex involved in sperm cell hyperactivation. Sperm cell hyperactivation is needed for sperm motility which is essential late in the preparation of sperm for fertilization. Required for CatSper complex targeting and trafficking into the quadrilinear nanodomains. Targets the preassembled CatSper complexes to elongating flagella, where it links the channel-carrying vesicles and motor proteins.
Synonyms: ALS2CR11; C2CD6; FLJ25351; SPGF68
Tractability: Antibody: its Gene Ontology location is reachable by antibodies, with medium confidence. PROTAC: ubiquitination databases record sites on it.
Gene: Protein-coding gene on chromosome 2 (201,487,421 to 201,619,178, reverse strand). Ensembl gene ENSG00000155754.
Subcellular location: Cell projection, cilium, flagellum membrane
Subcellular location (Human Protein Atlas): Principal piece; Acrosome; Equatorial segment
Gene Ontology:
Molecular function: protein binding
Biological process: flagellated sperm motility; sperm capacitation; spermatogenesis; vesicle-mediated transport to the plasma membrane
Cellular component: sperm principal piece; CatSper complex
Genetic constraint (gnomAD): Loss-of-function variants: 102 observed, 132.46 expected, observed/expected ratio (o/e) 0.77, 90% interval 0.65 to 0.91. The synonymous counts are far from expectation, so gnomAD's model fits this gene poorly and the ratio says little. Missense variants: 1,552 observed, 1,954.8 expected, observed/expected ratio (o/e) 0.79, 90% interval 0.76 to 0.83. Synonymous variants: 569 observed, 684.69 expected, observed/expected ratio (o/e) 0.83, 90% interval 0.77 to 0.89.
Homologues: Orthologues: chimpanzee C2CD6 (97% identical), macaque C2CD6 (92% identical), dog C2CD6 (63% identical), mouse C2cd6 (51% identical), rat C2cd6 (51% identical).
Diseases named in the same sentence as CATSPERT in open-access papers:
CATSPERT is named in the same sentence as 3 diseases in open-access papers, as found by Europe PMC text mining. Sharing a sentence is not in itself a finding about the gene and the disease.
CATSPERT shares sentences with these, for which no sentence is quoted: Globozoospermia (1 paper); lung carcinoma (1); oligospermia (1).